KLF6 (KLF transcription factor 6)
Description:
Transcriptional activator (By similarity). Binds a GC box motif. Could play a role in B-cell growth and development.
Synonyms: BCD1; COPEB; CPBP; ST12; GBF; Zf9; PAC1; CBA1
Tractability: PROTAC: ubiquitination databases record sites on it.
Gene: Protein-coding gene on chromosome 10 (3,775,996 to 3,785,281, reverse strand). Ensembl gene ENSG00000067082.
Subcellular location: Nucleus
Subcellular location (Human Protein Atlas): Nucleoplasm; Cytosol; Nucleoli; Nucleoli fibrillar center; Vesicles
Gene Ontology:
Molecular function: DNA-binding transcription activator activity, RNA polymerase II-specific; protein binding; RNA polymerase II cis-regulatory region sequence-specific DNA binding; sequence-specific double-stranded DNA binding; DNA-binding transcription factor activity, RNA polymerase II-specific
Biological process: positive regulation of transcription by RNA polymerase II; B cell differentiation; positive regulation of DNA-templated transcription; regulation of transcription by RNA polymerase II
Cellular component: fibrillar center; nucleolus; nucleoplasm; chromatin; nucleus
Genetic constraint (gnomAD): Loss-of-function variants: 0 observed, 27.57 expected, observed/expected ratio (o/e) 0, 90% interval 0 to 0.11. The upper end of that interval is the gene's LOEUF score, 0.11, which puts it in group 1 of 6, group 1 being the genes least tolerant of losing a copy. Missense variants: 233 observed, 376.66 expected, observed/expected ratio (o/e) 0.62, 90% interval 0.56 to 0.69. Synonymous variants: 152 observed, 154.62 expected, observed/expected ratio (o/e) 0.98, 90% interval 0.86 to 1.12.
Homologues: Orthologues: chimpanzee KLF6 (99% identical), macaque KLF6 (99% identical), guinea pig KLF6 (96% identical), rabbit KLF6 (95% identical), mouse Klf6 (95% identical), pig KLF6 (93% identical), rat Klf6 (90% identical), dog KLF6 (84% identical), tropical clawed frog klf6 (77% identical), zebrafish klf6a (76% identical), Drosophila melanogaster luna (53% identical). Paralogues in human: KLF7 (56% identical), KLF5 (37% identical), KLF12 (34% identical), KLF3 (33% identical), KLF4 (33% identical), KLF2 (32% identical), KLF8 (30% identical), KLF1 (30% identical), KLF10 (27% identical), KLF11 (27% identical), KLF15 (27% identical), SP8 (26% identical), and 10 more.
Diseases named in the same sentence as KLF6 in open-access papers:
KLF6 is named in the same sentence as 161 diseases in open-access papers, as found by Europe PMC text mining. Sharing a sentence is not in itself a finding about the gene and the disease. The quoted sentences say what the papers report.
prostate carcinoma (46 papers, 2003 to 2025). A carcinoma that arises from epithelial cells of the prostate gland. "According to another study, a single KLF6 allele reduced the risk of prostate cancer by 77% in human subjects highlighting the tumor suppressor attribution of KLF6." (PMID 36292712, 2022). "This KLF6 alternative splicing was induced by the G > A germline mutation at the intervening sequence 1-27, in which this mutation was first identified in prostate cancer cases, which lead to alternative splicing." (PMID 32998281, 2020). "A SNP in KLF6 intron generates a novel functional SRp40 DNA binding site and increases three alternatively spliced KLF6 isoforms that are associated with prostate cancer and lung cancer." (PMID 30886859, 2019). "In prostate cancer, it has been reported that two isoforms of KLF6 lead to increased cell growth and an increased risk of prostate cancer." (PMID 27165105, 2016). "KLF6 gene is mutated in a subset of human prostate cancer and involved in human prostate cancer; it is also inactivated by loss of heterozygosity (LOH)." (PMID 26662959, 2016). "KLF6 has been reported as a tumor suppressor in prostate cancer and recently a splice variant thereof, KLF6-SV1, was identified as an oncogene in breast cancer with increased expression in breast tumors." (PMID 25593984, 2014). "In prostate cancer the intronic risk SNP was shown to lie within a splicing enhancer region of the KLF6 tumor-suppressor gene." (PMID 23752272, 2013). "KLF6 (Kruppel-like factor 6) is a tumor suppressor protein that is down-regulated or mutated in several types of cancers, including prostate cancer." (PMID 21552502, 2011). "Re-expression of wild type KLF6 into prostate carcinoma PC-3 cells and non-small lung cancer cells, which harbor loss-of-function mutations or downregulation of the endogenous klf6 gene, respectively, enhanced growth suppression and apoptosis." (PMID 20126619, 2010). "Again, the finding of a broad loss of KLF6 expression in prostate cancer is strongly challenged by independent studies reporting the infrequent germ-line mutation of KLF6, or the presence of KLF6 IVS1-27G>A polymorphism, in prostate cancer." (PMID 20119532, 2009). "This study proposes that variation at putative 8q24 cis-regulator(s) of transcription can significantly alter germline c-MYC expression levels and, thus, contribute to prostate cancer susceptibility by down-regulating the prostate tumor suppressor KLF6 gene." (PMID 18190704, 2008). "The KLF6 gene is inactivated in prostate cancer by loss of heterozygosity and/or by somatic mutations identified in tumors, cell lines and xenografts." (PMID 18190704, 2008). "A recent report suggests that the KLF6 gene encoding the Krüppel-like factor 6 protein is a frequently mutated, putative tumour suppressor gene in prostate cancer." (PMID 12915879, 2003). "The allelic loss and somatic mutations of KLF6 were observed in patients with sporadic prostate cancer and a germline single nucleotide polymorphism (SNP) in KLF6 gene IVS1-27 G > A is shown to cause aberrant splicing to generate 3 splice variants, KLF6-SV1, -SV2 and -SV3." (PMID 32106418, 2020). "In addition, KLF6 has been identified as a tumor suppressor gene associated mainly with prostate cancer." (PMID 21849067, 2011). "Our study further proposes that germline c-MYC overexpression may promote cellular transformation of the normal epithelium and, by extension, risk of prostate cancer by down-regulating the prostate tumor suppressor KLF6 gene." (PMID 18190704, 2008). "Owing to the high mutation frequency of KLF6 in a number of pituitary tumors, knowledge of these KLF6 polymorphisms may be important for prostate cancer diagnosis." (PMID 17201911, 2007). "If mutations that compromise function of the KLF6 transcription factor are indeed common in prostate cancer, we might then ask whether clustering analysis of data from molecular profiling of tumours would define KLF6 mutant tumours as a subgroup." (PMID 12915879, 2003).
prostate carcinoma (continued). "KLF6-SV1 overexpression significantly antagonized the ability of wild-type KLF6 (WtKLF6) to up-regulate p21 expression and inhibit cellular proliferation, which eventually led to increased cell proliferation while also significantly raising the risk of prostate cancer in males." (PMID 33816511, 2021). "In prostate cancer, KLF6 is considered a tissue-specific structure-specific prognostic marker for prostate cancer; inactivation or overexpression of KLF6 as a tumor suppressor produces a protumorigenic effect and facilitates tumor progression." (PMID 40149637, 2025). "KLF6 is a zinc finger transcription factor and a tumor suppressor, and was reported to directly bind to and activate the Aft3 promoter in prostate cancer cells." (PMID 39872376, 2024). "Overexpression of KLF6 in prostate cancer inhibits proliferation and induces apoptosis, showing that KLF6 functions as a prostate tumor suppressor." (PMID 35345512, 2022). "Studies have reported that a splice variant of KLF6, KLF6-SV1, is a cancer-promoting gene in ovarian and prostate cancer models." (PMID 36615000, 2022). "KLF6 is initially considered as a tumor suppressor in prostate cancer, and is regulated through activating CDHL promoter." (PMID 34524611, 2021). "In prostate cancer (PCa), the overall expression of KLF6 decreases with tumor progression in opposition to KLF6-SV1, which significantly increases in hormone-refractory metastases." (PMID 32244895, 2020). "Several independent studies have reported the absence of KLF6 genetic alterations in colorectal, liver, brain and prostate cancers, contradicting earlier studies that showed the frequent KLF6 inactivation in these cancer types." (PMID 32998281, 2020). "ATF3 is a crucial regulator of Kruppel-like factor 6 (KLF6)-induced apoptosis in prostate cancer cells." (PMID 32922364, 2020). "On the other hand, SRSF5 is indicated to be involved in pre-mRNA splicing of Kruppel-like factor 6 (KLF6) in prostate cancer." (PMID 32106418, 2020). "This analysis showed that the RHPN2 gene had significantly elevated expression in prostate cancer samples and interacted with KLF6 gene, which was the core gene in gene interaction network." (PMID 31847864, 2019). "The overexpression of KLF6 induced apoptosis in non-small-cell lung cancer and prostate cancer cells." (PMID 31723124, 2019). "Two of the genes verified in both primary cell lines, Klf6 and Ddit3, are markers of oxidative stress recently reported as upregulated by salinomycin in prostate cancer cells." (PMID 27612428, 2016). "KLF6, originally identified as a tumor suppressor in prostate carcinoma, also activates the CDH1 promoter." (PMID 24429391, 2014). "Overexpression of KLF6 also induced apoptosis in several human cancers, including prostate cancer, non-small cell lung cancer, and osteosarcoma." (PMID 24324791, 2013). "A germline KLF6 single nucleotide polymorphism (IVS1-27G>A), together with increased transcription of three alternatively spliced KLF6 isoforms is reported in prostate cancer." (PMID 20119532, 2009). "KLF6, a candidate tumor suppressor gene in prostate cancer, contains 283 aa and is present in many tissues, including placenta, heart, lung, liver and pancreas." (PMID 18053161, 2007). "Previously, several studies identified KLF6 as a tumor-suppressor gene due to frequent somatic inactivation of the KLF6 gene and/or downregulation of KLF6 expression in prostate carcinoma, glioblastoma, colorectal tumors, gastric cancer, hepatocellular carcinoma, and lung cancer." (PMID 36615000, 2022). "Early reports showed that KLF6 was frequently inactivated in sporadic prostate cancer cases." (PMID 32998281, 2020). "The modification in tumor suppressor KLF6 was responsible for the advancement of prostate cancer." (PMID 30970615, 2019).
prostate carcinoma (continued). "ATF-3 is a key mediator of KLF6-induced apoptosis in prostate cancer cells." (PMID 28380462, 2017). "However, significant genetic alterations of KLF6 seem restricted to a minority of high-grade prostate cancers." (PMID 20119532, 2009). "KLF6 SV1 is demonstrated to be essential for prostate cancer cell growth and spread." (PMID 20119532, 2009). "Taken together, KLF6 SV1 is a novel therapeutic target for prostate cancer." (PMID 20119532, 2009). "Similarly, KLF6 induces ATF3 overexpression promotes apoptosis in human prostate cancer cells." (PMID 31410216, 2019). "Therefore, ATF3 is a key mediator of KLF6-induced apoptosis in prostate cancer cells." (PMID 24222778, 2013). "Recently, the regulatory role of KLF6 in ATF3 expression was verified in endothelial cells, pancreatic cancer cells, and prostate cancer cells." (PMID 39872376, 2024). "In another motif combination predicted in both breast cancer and colorectal cancer, KLF6 and SP1, these two TFs together initiate the transcription of CERS2 in human prostate carcinoma cells." (PMID 28684851, 2017). "These included 8 genes differentially expressed in lethal prostate cancer and highly functionally related to NFκB along with additional promising candidates such as CXCL1, KLF6, and IRF1." (PMID 27078000, 2016). "This is complementary with our predictions, suggesting that after being regulated by KLF6, ZFP36 directly binds to NEDD9, thus acting as another novel upstream inhibitor of NFκB with a role in the amelioration of prostate cancer." (PMID 27078000, 2016). "KLF6 has been shown to be acetylated and to interact with CBP and PCAF in prostate cancer cells in vivo, contributing to the up-regulation of p21WAF1/cip1 gene expression." (PMID 23418492, 2013). "Kruppel-like factor 6 (KLF6) is a zinc finger transcription factor and functions as tumor suppressor gene in human prostate cancer." (PMID 22347457, 2012). "KLF6SV1 is upregulated in prostate cancer tumors compared with normal prostate tissue and the activity of one of the splice isoforms KLF6SV1 directly opposes KLF6 effects on cell proliferation, colony formation, invasion, and in vivo tumor growth." (PMID 22419853, 2012). "Again, tumor-derived KLF6 mutants fail to transactivate p21WAF1/CIP1, and to impede cell proliferation, when wild type KLF6 induces apotosis in prostate cancer cells via the ATF3 transcription factor." (PMID 20119532, 2009). "A 5-gene recurrence predictor of prostate cancer contains KLF6, three common ARACNe-based predictions between MYC and KLF6 (FOS, JUNB and ZFP36), and PPFIA3, which is functionally related to another predicted target of KLF6 (PPFIBP2)." (PMID 18190704, 2008). "Besides, the treatment with lovastatin, a hypercholesterolemia drug, was also able to induce the expression of KLF6 in cisplatin-resistant HCP4 cervical cancer and PCDP5 prostate cancer cells, leading to cell cycle arrest and apoptosis." (PMID 32998281, 2020). "Notable genes in the predicted pathway included ATF3, JUNB, KLF6, NR4A2, ZFP36, DUSP5 and NEDD9, as well as STAT3 and IRF1 as novel upstream regulators, and SELE, CXCL1 and CXCL2 as novel downstream targets of NFκB in prostate cancer." (PMID 27078000, 2016).
breast cancer (30 papers, 2007 to 2025). A primary or metastatic malignant neoplasm involving the breast. "Regarding genes regulated by MMRs, we discovered a redundant regulation of the tumor suppressors FAT4 and KLF6, among others, whose loss of expression has been associated with a more aggressive phenotype in breast cancer." (PMID 32635183, 2020). "KLF6 and its transcript variants have been implicated in the breast cancer metastasis and it is found to be up regulated in many tumors." (PMID 25781993, 2015). "Notably, splicing of hMENA may improve the early diagnosis of breast cancer and clinical decision, whereas the balance between splicing variants of KLF6 and caspase-9 genes could be useful to predict the susceptibility of cancer cells to chemotherapy." (PMID 24285959, 2013). "LncRNA Xist knockout inhibited the expression of C/EBPα and KLF6 and induced the transformation from M1 to M2, thus promoting the proliferation and migration of breast cancer cells." (PMID 35145526, 2022). "The lncRNA BCRT1/miR-1303/PTBP3 and lncRNA Xist/miR-101-3p/KLF6/C/EBPα can regulate the progression of breast cancer." (PMID 35145526, 2022). "Targeting KLF6 in the breast cancer cell line reduced the cells’ proliferative capacity, denoting KLF6 pro-oncogenic roles in breast cancer." (PMID 32998281, 2020). "Kruppel-like factor 6 (KLF6) is a tumor-suppressing protein whose expression is reduced in a majority of breast cancer patients." (PMID 31065692, 2019). "spleen tyrosine kinase isoform-S (SkyS) and human epidermal growth factor receptor (HER-2) in breast cancer, B-cell lymphoma-extra large (Bcl-xL), Kruppel-like factor 6 (KLF6) and peroxisome proliferator-activated receptor gamma 1 (PPARγ1) in lung cancer etc." (PMID 25034693, 2014). "KLF6 expression and sub-cellular distribution was further analyzed in breast cancer samples, mainly focused on ductal breast tumor tissue cases." (PMID 20126619, 2010). "Expression of KLF6 was further analyzed in breast cancer tissues overexpressing ERBB2 oncoprotein, which is associated with poor disease prognosis and patient's survival." (PMID 20126619, 2010). "The knowledge of the complete set of target genes regulated by KLF6 in ductal breast cancer is a huge task to be undertaken to gain further insights about KLF6 in this pathology." (PMID 20126619, 2010). "Results indicate that while both nuclear and cytoplasmic distribution of KLF6 is detected in normal breast tissues, breast carcinomas express KLF6 mainly detected in the cytoplasm." (PMID 20126619, 2010). "Homo sapiens (hsa)-miR-4262 has been reported to participate in paclitaxel resistance in non-small cell lung cancer by regulating PTEN, and it promotes the proliferation and invasion of human breast cancer cells directly by targeting kruppel-like 6 (KLF6) and KLF15." (PMID 33821195, 2021).